SCYL2 (SCY1 like pseudokinase 2)
Description:
Component of the AP2-containing clathrin coat that may regulate clathrin-dependent trafficking at plasma membrane, TGN and endosomal system (Probable). A possible serine/threonine-protein kinase toward the beta2-subunit of the plasma membrane adapter complex AP2 and other proteins in presence of poly-L-lysine has not been confirmed. By regulating the expression of excitatory receptors at synapses, plays an essential role in neuronal function and signaling and in brain development (By similarity).
Synonyms: CVAK104; KIAA1360; AMC4; AMCNACC
Tractability: Small molecule: it belongs to a druggable protein family. Antibody: UniProt places it where antibodies can reach, with high confidence. PROTAC: ubiquitination databases record sites on it; its protein half-life has been measured.
Gene: Protein-coding gene on chromosome 12 (100,266,830 to 100,341,728, forward strand). Ensembl gene ENSG00000136021.
Subcellular location: Cytoplasmic vesicle, clathrin-coated vesicle; Golgi apparatus, trans-Golgi network membrane; Endosome membrane
Gene Ontology:
Molecular function: protein binding; signaling receptor binding; ATP binding; protein kinase activity
Biological process: clathrin-dependent endocytosis; endosome to lysosome transport; negative regulation of canonical Wnt signaling pathway; receptor internalization; brain development; pyramidal neuron development
Cellular component: endosome membrane; clathrin-coated vesicle; Golgi apparatus
Genetic constraint (gnomAD): Loss-of-function variants: 19 observed, 56.76 expected, observed/expected ratio (o/e) 0.33, 90% interval 0.23 to 0.49. The upper end of that interval is the gene's LOEUF score, 0.49, which puts it in group 2 of 6, group 1 being the genes least tolerant of losing a copy. Missense variants: 566 observed, 706.78 expected, observed/expected ratio (o/e) 0.8, 90% interval 0.75 to 0.86. Synonymous variants: 209 observed, 229.42 expected, observed/expected ratio (o/e) 0.91, 90% interval 0.81 to 1.02.
Homologues: Orthologues: macaque SCYL2 (99% identical), pig SCYL2 (97% identical), chimpanzee SCYL2 (95% identical), rat Scyl2 (94% identical), mouse Scyl2 (93% identical), guinea pig SCYL2 (89% identical), rabbit SCYL2 (89% identical), dog SCYL2 (84% identical), tropical clawed frog scyl2 (78% identical), zebrafish scyl2 (71% identical), Drosophila melanogaster CG1951 (39% identical), Caenorhabditis elegans ZC581.9 (21% identical). Paralogues in human: SCYL1 (17% identical), SCYL3 (13% identical).
Diseases named in the same sentence as SCYL2 in open-access papers:
SCYL2 is named in the same sentence as 22 diseases in open-access papers, as found by Europe PMC text mining. Sharing a sentence is not in itself a finding about the gene and the disease. The quoted sentences say what the papers report.
gastric cancer (2 papers, 2023 to 2024). A primary or metastatic malignant neoplasm involving the stomach. "The GluProRS interactions with the tRNA-dihydrouridine synthase 2 (DUS2) in lung cancer and with the SCY1-like protein 2 (SCYL2) in gastric cancer drive cell proliferation and have tumorigenic effects." (PMID 38255739, 2024).
arthrogryposis multiplex congenita (1 paper, 2025). Arthrogryposis multiplex congenita (AMC) is a group of disorders characterized by congenital limb contractures. "SCYL2, whose product is involved in the agenesis of Corpus Callosum causing Arthrogryposis Multiplex Congenita, was found to be affected by a novel homozygous deleterious variant (Leu574Pro) (VUS) in one of our patients, EPBL-0189." (PMID 40565278, 2025).
aspiration pneumonias (1 paper, 2025). "The combination of recurrent viral infections and aspiration pneumonias in our patient may reflect dual pathogenic mechanisms: impaired antiviral responses due to SCYL2’s role in viral particle release regulation and increased aspiration risk due to bulbar dysfunction." (PMID 40243816, 2025).
autonomic dysfunction (1 paper, 2025). "In this case report, we describe the clinical presentation of an infant with novel homozygous mutations in SCYL2 with microcephaly, arthrogryposis multiplex, optic atrophy, epilepsy, recurrent infections, autonomic dysfunction, and agenesis of the corpus callosum." (PMID 40243816, 2025).
breast carcinoma (1 paper, 2015). "Of note, SCYL2 is expressed in breast cancer and is involved with clathrin-dependent vesicle trafficking." (PMID 26420498, 2015).
COVID-19 (1 paper, 2023). A disease caused by infection with severe acute respiratory syndrome coronavirus 2. "We found the strongest association between SCYL2 and severe COVID-19." (PMID 37547597, 2023). "We found six genes at locus 3p21.31 significantly associated with severe COVID-19: LZTFL1, FYCO1, XCR1, CCR9, TMLHE-AS1, and SCYL2." (PMID 37547597, 2023). "We found significant associations between COVID-19 and LZTFL1, FYCO1, XCR1, CCR9, TMLHE-AS1, and SCYL2 at 3p21.31." (PMID 37547597, 2023).
developmental delay (1 paper, 2025). "Neurogenic arthrogryposis due to SCYL2 mutations, also known as arthrogryposis multiplex congenita 4 (AMC4), is a rare condition that presents with microcephaly, agenesis of the corpus callosum, optic atrophy, global developmental delay, and early lethality." (PMID 40243816, 2025).
dysautonomia (1 paper, 2025). An acute or chronic disorder, affecting the sympathetic or parasympathetic nervous system. "Given the link between proper Golgi apparatus structure and function and motor neuron survival, it is plausible that the dysautonomia, as part of the motor neuron disease observed in our patient, is linked to SCYL2’s function in the trans-Golgi network." (PMID 40243816, 2025). "The presence of dysautonomia extends our understanding of SCYL2’s role beyond the central nervous system, suggesting its importance in peripheral nervous system function through the regulation of vesicular trafficking in autonomic neurons." (PMID 40243816, 2025).
upper respiratory tract infections (1 paper, 2025). "This antiviral feature of SCYL2, and its dysfunction in our patient, may have played a role in the recurrent upper respiratory tract infections observed, although infections were not reported in any of the other patients with SCYL2 mutations." (PMID 40243816, 2025).
cancer (2 papers, 2022 to 2023). A tumor composed of atypical neoplastic, often pleomorphic cells that invade other tissues. "In this study, it is worth mentioning that the AAGAB and SCYL2 expressions were lower in the cancer samples, but there were found to be risk factors through the Cox analysis." (PMID 37740762, 2023). "As the only bifunctional enzyme in the ARS family, EPRS activates the WNT/GSK-3β/β-catenin signaling pathway and stimulates the accumulation of β-catenin in the nucleus by directly binding to SCYL2 (SCY1-like protein 2), promoting cancer cell proliferation." (PMID 36017335, 2022). "The TMEM251, AAGAB, ENTR1, SCYL2, and WDR72 were all found to be expressed mainly in cancer cells." (PMID 37740762, 2023).
tumor (2 papers, 2023 to 2026). "However, as risk genes for poor prognosis, the AAGAB and the SCYL2 expressions were found to be decreased in the tumor tissues at both mRNA and protein levels." (PMID 37740762, 2023). "SCYL2-associated complex phosphorylates PTEN at STT, and SCYL2 downregulation has anti-tumor effects in ATL via inhibition of the PI3K/AKT signaling pathway by dephosphorylating PTEN at STT." (PMID 41703271, 2026). "Our results indicate that SCYL2/CHC complex plays a pivotal role in regulating the PI3K/AKT signaling pathway through PTEN phosphorylation, thus leading to tumor development and may be a promising novel target for treating tumors." (PMID 41703271, 2026).
SCYL2 also shares sentences with these, for which no sentence is quoted: adult T-cell leukemia (1 paper); amyotrophic lateral sclerosis (1); epilepsy (1); lung carcinoma (1); lymphoma (1); microcephaly (1); motor neuron disease (1); neurodegenerative disease (1); neurodevelopmental disorder (1); optic atrophy (1); viral infections (1).